JAK2 (Janus kinase 2)
Diseases named in the same sentence as JAK2 in open-access papers (continued):
Sharing a sentence is not in itself a finding about the gene and the disease.
Stroke (46 papers, 2011 to 2026). Sudden impairment of blood flow to a part of the brain due to occlusion or rupture of an artery to the brain. "Where appropriate, further investigations, including a young stroke blood panel, should be performed to evaluate for conditions such as antiphospholipid syndrome, JAK2 mutation, or paroxysmal nocturnal hemoglobinuria." (PMID 41409924, 2025). "Our patient was considered to be at high risk for thrombosis because of his age >60 years, history of stroke and diabetes, and the JAK2 V617F mutation, which should be treated with a combination of low-dose ASA and hydroxyurea." (PMID 40926892, 2025). "These mutations, notably in genes like DNMT3A, TET2, and JAK2, induce pro-inflammatory and pro-atherosclerotic processes, promoting vascular damage and stroke risk." (PMID 39997650, 2025). "Individuals with CHIP, particularly those with a high variant allele frequency (VAF ≥ 10%) or specific mutations such as JAK2, are at a heightened risk for myocardial infarction, stroke, and heart failure." (PMID 40214958, 2025). "According to current guidelines, in cases where a JAK2 mutation is confirmed and arterial thrombotic events such as stroke have occurred, treatment with hydroxyurea in combination with twice-daily aspirin is recommended." (PMID 37512112, 2023). "A novel JAK2 variant (p.Arg1063His) was described in a patient with embolic stroke of undetermined etiology (ESUS) and familial clustering of ischemic juvenile stroke." (PMID 36411388, 2023). "In this study, our results showed that astrocytic IL-17A promoting post-stroke angiogenesis in enriched animals might be linked with the upregulation of IL-6, JAK2, and STAT3, and moreover, that this promoting effect was neutralized by anti-IL-17 mAb." (PMID 36873773, 2023). "The ability of JB to modulate microglial polarization through JAK2/STAT3 inhibition presents a promising pharmacological approach for cerebral ischemia–reperfusion injury management in stroke therapy." (PMID 41254929, 2025). "Post-stroke, neurons release soluble Fas ligand (sFasL), which activates the phosphorylation cascade of the JAK2/STAT3/NF-κB pathway." (PMID 38887610, 2024). "Studies on stroke have shown increased phosphorylation levels of JAK2 and STAT3 in the cortical and striatal regions of rat brains." (PMID 38887610, 2024). "IL‐6 is a cytokine engaged in the proinflammatory process after stroke, which is mediated by the Janus kinase 2 (JAK2) and the signal transducer and activator of transcription 3 (STAT3) pathway." (PMID 37143406, 2023). "The V617F mutation in the Janus kinase 2 (JAK2) gene is one of the most typical mutations in ET and has been shown to be a risk factor for stroke, especially in younger people." (PMID 36397023, 2022). "It has been shown recently that pretreatment with a Jak2 inhibitor (AG490) in a rodent stroke model alleviated brain endothelial cell barrier disruption and decreased the reduction of tight junction ZO-1 protein caused by IL-6." (PMID 36145501, 2022). "Resveratrol considerably improved neurological function and inhibits the apoptosis of neuron cells after stroke, which is partially induced by activation of the JAK2/STAT3/PI3K/AKT/mTOR signaling pathway." (PMID 36278158, 2022). "A recent study on non-erythropoietic mutant erythropoietin (MEPO) showed that increased STAT3 phosphorylation was involved in the neuronal protection provided by MEPO in stroke mice using the specific inhibitor AG490 to block JAK2/STAT3 activation." (PMID 35578342, 2022). "Our data further demonstrated that astrocytic ET-1 promoted proliferation of neural progenitor cells and their differentiation into astrocytes after stroke via the Jak2/Stat3 pathway and thus contributed to more severe brain damage after stroke." (PMID 31733648, 2019).
Stroke (continued). "Taken together, these findings indicated that astrocytic endothelin-1 overexpression promoted neural progenitor cell proliferation and differentiation into astrocytes via the Jak2/Stat3 pathway in murine models of stroke." (PMID 31733648, 2019). "In primary cortical neurons and murine models of stroke, the activation of the Jak2/Stat3 pathway by secretoneurin has been found to exert neuroprotective effects and induce neuronal plasticity after hypoxia and ischemic insult." (PMID 25092271, 2014). "EPO and EPOR also induce neurogenesis after stroke, early during embryonic development and in vitro via Jak2/Stat3 and PI3K/AKT pathway activation." (PMID 21777449, 2011). "However, in stroke models, the up-regulation of miR-216 is shown to be beneficial for inducing neuroprotection against cerebral ischemia by targeting JAK2." (PMID 39337512, 2024). "In addition, the Janus kinase 2/signal transducer and activator of transcription 3 (JAK2/STAT3) pathway is known to be abnormally activated in stroke, and this combination treatment appears to decrease this abnormal activation." (PMID 34944727, 2021). "Overall, the findings of the present study further confirmed our hypothesis that astrocytic endothelin-1 overexpression promotes neural progenitor cell proliferation and differentiation into more astrocytes after stroke via the Jak2/Stat3 pathway." (PMID 31733648, 2019). "However, the exact mechanism through which astrocytic endothelin-1 affects the Jak2/Stat3 pathway in a murine stroke model need would benefit from further investigation in the future." (PMID 31733648, 2019). "Studies have shown that the activation of the JAK2/STAT3 pathway after experimental stroke could improve functional performance and/or decrease cell apoptosis." (PMID 28848617, 2017). "In addition, young stroke blood screen tests ruled out the possibility of connective tissue disease, vasculitis, antiphospholipid syndrome, homocystinuria, JAK-2 mutation, or paroxysmal nocturnal hemoglobinuria." (PMID 41409924, 2025). "Furthermore, NLRP3 inflammasome activation after stroke may be related to the induction of cytokine storm-related proinflammatory cytokines, which can be relieved by Rux via its targeting of the JAK2/STAT3 pathway." (PMID 34367186, 2021). "Since both the EPO/EpoR and the JAK2/STAT3 pathways have been implicated as molecular targets for ischemic stroke prevention and treatment, the activation of both of these cell pathways and their downstream signaling cascades is recognized as a promising therapeutic approach for stroke patients." (PMID 28848617, 2017). "They found that stroke was not related to platelet number but rather to JAK2 mutation status." (PMID 27094255, 2016). "However, the precise role of JAK2/STAT3 activation after stroke remains unclear." (PMID 36419252, 2023). "Several groups have reported that the JAK2/STAT3 pathway is activated in in vitro and in vivo experimental models of stroke." (PMID 36419252, 2023). "The JAK2/STAT3 pathway has been highlighted by in vitro and in vivo experimental stroke models, subsequently activating numerous genes responsible for many cellular functions in neural injury and repair." (PMID 35055089, 2022). "The research group confirmed that catalpol promotes angiogenesis and maturation after stroke, which is closely related to the upregulation of VEGF/KDR protein expression and the regulation of Jak2/Stat3 signal." (PMID 33505489, 2021). "The levels of numerous proinflammatory cytokines are elevated by the JAK2/STAT3 pathway, and these cytokines play a crucial role in pathological injury in stroke." (PMID 34367186, 2021). "Expression of SCG2 is modulated by extracellular calcium, and it can induce expression of the anti-apoptotic protein Bcl2 through activation of JAK2/STAT3 signaling, providing protection in a murine stroke model." (PMID 30670947, 2018).
Stroke (continued). "It has been reported that activation of the JAK2/STAT3 pathway could induce the production of IL‐6 and exacerbate stroke‐induced brain injury." (PMID 37143406, 2023). "All the patients had a negative JAK2 status and two had already experienced vascular complications prior to the diagnosis of MDS, including stroke and myocardial infarction." (PMID 24260071, 2013).
diabetes (44 papers, 2012 to 2025). "This study provides preclinical validation for repurposing JAK1/JAK2 inhibitors to mitigate checkpoint inhibitor-associated diabetes while preserving anticancer immunity." (PMID 40534861, 2025). "Our results suggest that diabetes caused notable increases in the phosphorylation of JAK2 and STAT3 and the levels of TGF-β1." (PMID 36597092, 2023). "Multivariate MR analysis revealed that there was still a significant causal relationship between JAK2 and ED under the effect of adjusting diabetes (OR = 1.084, 95% CI = 1.013–1.154, p = 0.026)." (PMID 37407943, 2023). "The phenotypic shift of vascular smooth muscle cells in diabetic animal models is caused by the RAGE/JAK2/STAT3 pathway in the maintenance of diabetes-mediated circulatory problems through the modification of kinetics in mitochondria." (PMID 36497125, 2022). "Patients with UE injuries who are active smokers and who also have diabetes, hypertension, hypothyroidism, cancer, coagulation disorder (JAK2 gene V617F mutation), or a central venous catheter may benefit from anticoagulant prophylaxis." (PMID 37519534, 2023). "JAK2-dependent inflammatory mechanisms associated with diabetes were mediated by SAA in podocytes." (PMID 30763329, 2019). "In rodent models, JAK2 was activated in the penile tissue of diabetic mice, and tamoxifen-induced JAK2 deficiency ameliorated impaired erectile function induced by diabetes, which may be mediated by a reduction in oxidative stress, apoptosis, and cavernous fibrosis." (PMID 37407943, 2023). "In NOD mice with anti–PD-L1–induced hyperglycemia, administration of a JAK1/JAK2 inhibitor resulted in the reversal of diabetes." (PMID 40534861, 2025). "The diabetes model group's JAK2 and STAT1 mRNA expression levels were found to be considerably higher than those in the normal group (p < 0.05), and taurine treatment dramatically decreased these levels (p < 0.01)." (PMID 38560269, 2024). "Compared to the findings in normal mice, FN-γ, SOCS1, STAT3, IFITM3, IRF3, and JAK2 expression was significantly higher in spleen cells from mice with diabetes, suggesting homeostatic inflammation was induced." (PMID 37110462, 2023). "Taken together, our data indicated that long-term aerobic exercise improves type 2 diabetes mellitus-related cognitive impairment by inhibiting JAK2/STAT3 and enhancing AMPK/SIRT1 pathways in mice." (PMID 35578689, 2022). "The JAK2/STAT3/SOCS axis plays a crucial role in the development of diabetes, where overexpression and phosphorylation of JAK2 were observed." (PMID 34067609, 2021). "Serum amyloid A (SAA), a potent inflammatory mediator, and Janus kinase 2 (JAK2), an intracellular signaling kinase, are increased by diabetes." (PMID 30763329, 2019). "Antioxidant NAC preserves RPC-induced cardioprotection by improving Cav-3-dependent Akt and STAT3 activation and by facilitating the cross talk between PI3K/Akt and JAK2/STAT3 signaling pathways in diabetes." (PMID 31583053, 2019). "Kidney mRNA and protein for SAA3 along with serum SAA3 were analyzed to determine the effect of diabetes and JAK2 overexpression at the tissue and systemic levels, respectively." (PMID 30763329, 2019). "Exposure of cultured podocytes to AGE, a diabetes-like condition, increased JAK2 activity and induced expression of SAA3 as well as pro-inflammatory mediators including Cxcl5, Ccl2, and Ccl5." (PMID 30763329, 2019). "Podocyte JAK2 overexpression in diabetes independently and synergistically increased SAA in the mouse kidney, which directly correlated with glomerular damage." (PMID 30763329, 2019). "In podocytes exposed to a diabetes-like condition, JAK2 inhibition reduced expression of SAA, while SAA knockout blocked expression of associated pro-inflammatory mediators." (PMID 30763329, 2019). "This study investigated the role of the JAK2/STAT3/SOCS pathway in type 2 diabetes mellitus (T2DM) and macrovascular complications (DV) (T2DM+DV) conditions." (PMID 29228585, 2017).
diabetes (continued). "Consequently, in clinical practice, the treatment of diabetes‐induced ED often involves the inhibition of JAK2 and the reduction of oxidative stress." (PMID 39245800, 2024). "It has been reported that CBL might alleviate endothelial dysfunction in patients with diabetes mellitus by inactivating the JAK2/STAT4 signalling pathway." (PMID 36726727, 2023). "In response to myocardial injury, diabetes caused a larger infarct size accompanied by decreased cardiac protection of phosphorylated Phosphoinositide 3-kinase (PI3K)/Akt and Janus kinase 2 (JAK2)/STAT3 and cardiac NO levels and these parameters were reversed by antioxidants treatment." (PMID 32751309, 2020). "Taken together, the present data show SAA to be a downstream mediator of JAK2 that may mechanistically contribute to podocyte-derived inflammation and consequent kidney damage in diabetes." (PMID 30763329, 2019). "It has been suggested that diabetes-related oxidative stress may induce vascular IL-6 expression and activate IL-6R and gp130, which in turn activates the JAK2/STAT3 signaling cascade." (PMID 22553973, 2012). "However, it remains unclear whether the compromised RPC cardioprotection in diabetes is an independent manifestation of hyperglycemia-induced oxidative stress or linked to impaired Cav-3 expression and PI3K/Akt and JAK2/STAT3 signaling." (PMID 31583053, 2019). "The coefficients for each parameter were as follows: 0.4029 for abnormal NT-pro BNP, 0.1706 for history of diabetes, 0.6376 for NPM1, 0.0294 for FLT3, 0.0383 for Ras, 0.1220 for WT1, 0.5206 for JAK2, 0.0055 for WBC, 0.0942 for RBC, and − 0.0007 for EF." (PMID 38273254, 2024). "SEA-treated spleen cells from mice with diabetes exhibited little change in the expression of STAT3, IFITM3, and JAK2." (PMID 37110462, 2023). "This indicated that exercise inhibited the JAK2/STAT3 pathway, which is likely one of the mechanisms by which aerobic exercise improves the symptoms of diabetes." (PMID 35578689, 2022). "In summary, the current results demonstrate that hyperglycemia-induced oxidative stress is involved in the impaired Cav-3-modulated PI3K/Akt and JAk2/STAT3 signaling, which ultimately compromises RPC cardioprotection in diabetes." (PMID 31583053, 2019). "In fact, high glucose levels induce angiotensin II-dependent activation of Jak2, Stat1, Stat3, and Stat5 and increase of TGF-β and fibronectin synthesis in rat mesangial cells of streptozotocin-induced diabetes." (PMID 26872211, 2016). "Myocardial STAT3 is an important transcription factor in the SAFE pathway (i.e., JAK2/STAT3 signaling cascade), especially during myocardium ischemia reperfusion injury, but cardiac p-STAT3 is reduced in diabetes." (PMID 23853776, 2013). "Our pre-clinical data show that inhibitors of JAK1/JAK2 prevent diabetes and reverse newly diagnosed diabetes in the T1D non-obese diabetic mouse model." (PMID 35606820, 2022). "Our pre-clinical data show that inhibitors of JAK1/JAK2 prevent diabetes and reverse newly diagnosed diabetes in the non-obese diabetic (NOD) mouse model of T1D." (PMID 35606820, 2022). "Prolactin can protect β-cells from ER stress through the JAK2/STAT5 pathway, transcription factors such as GLIS3 can enhance INS gene expression, rapamycin can improve diabetes and further down-regulate β-cell apoptosis, and induced pluripotent stem cells can promote β-cell regeneration." (PMID 36686471, 2022). "Antioxidant treatment with NAC could restore RPC-induced cardioprotection in diabetes by improving Cav-3-dependent Akt and STAT3 activation and by facilitating the cross talk between PI3K/Akt and JAK2/STAT3 signaling pathways." (PMID 31583053, 2019). "Differences in SAA3 protein in the glomeruli were not present by diabetes status or JAK2 overexpression." (PMID 30763329, 2019). "The diabetes-induced decrease of Cav-3 expression may lead to caveola dysfunction, which plays a vital role in affecting PI3K/Akt and JAK2/STAT3 signaling in diabetic hearts." (PMID 31583053, 2019).
diabetes (continued). "Therefore, using a model of myocardial injury in type 2 diabetic mellitus (T2DM) rats, the aim of this study was to investigate the potential effect of OMT on myocardial injury and elucidate the role of the Nrf2/HO-1 and JAK2/STAT3 signaling pathways in diabetic rats." (PMID 36597092, 2023). "JAK2 has a negative impact on synapse formation and insulin sensitivity in diabetes." (PMID 35578689, 2022). "Plasma SAA3 was not increased by diabetes or JAK2 overexpression." (PMID 30763329, 2019). "Diabetes increased the UACR, but JAK2 overexpression did not significantly increase it." (PMID 30763329, 2019).